FOXP3 (forkhead box P3)
Diseases named in the same sentence as FOXP3 in open-access papers (continued):
Sharing a sentence is not in itself a finding about the gene and the disease.
tumor (continued). "Interaction of PD-L1 with PD-1 receptor leads to inhibition of T-cell activation, CD8+ cytotoxic T-cells apoptosis, and increase of Foxp3+ Tregs number, which contributes the tumor to evade the immunity." (PMID 36430322, 2022). "It has been shown that the AREG protein secreted by tumor cells of lung adenocarcinoma can maintain the Treg suppressive function via the EGFR/GSK-3β/FOXP3 axis in vitro and in vivo." (PMID 35497874, 2022). "In the meantime, when FoxP3+ cells were detected within the tumor, the Treg expansion was correlated with the attenuation of worse prognosis." (PMID 35874749, 2022). "We found that the density of FOXP3+, PD-1+ and PD-L1+ cells in tumor tissues increased when the density of CD8+ T cells was increased compared with that in adjacent normal tissues." (PMID 35222387, 2022). "It has been proven that kynurenine from tryptophan metabolism in cancer cells can induce the expression of FOXP3, a marker of regulatory T cells (Tregs), by activating the AhR nuclear transform to suppress tumor immunotherapy." (PMID 35571116, 2022). "IL-28B reduced the frequency of splenic CD4+Foxp3+ cells in H22 tumor-bearing mice and the percentage of Foxp3+ cells after adding IL-28B at 5, 50, or 400 ng/ml." (PMID 35935577, 2022). "Consistently, Piezo1-/- tumor-bearing mice had more Foxp3+ Treg cells and fewer IFNγ+ TH1 cells in tumor tissue compared with WT control." (PMID 35993548, 2022). "We identified that radiation therapy significantly increased the proportion of CD4+FoxP3+CD25+ T regulatory cells in the tumor following radiation therapy (RT vs. Isotype p < 0.01) (Fig. 5aiii) as has previously been described." (PMID 36056093, 2022). "A2AR blockade reduces CD4+ FOXP3+ Tregs infiltration and enhances the anti-tumor response of CD8+ T cells by attenuating hypoxic HIF-1α signaling." (PMID 36532071, 2022). "This was the case with TIL Foxp3 levels unique relative to age, gender, TNM stage, HPV infection as well as rate of stromal desmoplasia, nuclear polymorphism, and tumor invasion." (PMID 35326661, 2022). "Numerous antigens, including self-antigens, are expressed by tumors, but infiltrating (CD4 + CD25 + Foxp3 +) Treg cells dampen the immune response, stopping it from attacking tumor cells." (PMID 34275008, 2022). "The number of tumor-infiltrating Tr1 cells (CD4+ FoxP3- IL-13- IL-10+) was associated with tumor-infiltrating pDCs, which enhanced Tr1-produced IL-10 via ICOS-L when exposed to tumor-derived factors." (PMID 35619702, 2022). "Lymph node specimens were immunohistochemically analyzed for CD8+, FoxP3+, and CD79a+ lymphocytes, CD204+ tumor‐associated macrophages (TAMs), and alpha‐smooth muscle actin‐positive cancer‐associated fibroblasts (αSMA+ CAFs)." (PMID 35023268, 2022). "In tumor-bearing animals, IL-27 downregulated the expression of FoxP3 in CD4+ and CD8+ T cells and prevented generation and expansion of Tregs, immunosuppressive T cells which inhibited antitumor immunity in IL-10- and TGF-β-dependent manner." (PMID 35757015, 2022). "This selective depletion also contributed toward CD3+Foxp3+Treg cells infiltration into the tumor stroma, which ultimately increased tumor aggressiveness and reduced animal survival." (PMID 36324128, 2022). "Previous study demonstrated that FOXP3 + Treg cell infiltration in tumor islets predicted a poor prognosis in NSCLC (HR: 3.91, P < .001)." (PMID 36550816, 2022). "It has been demonstrated that the tumor-derived TGF-β induced extrathymic conversion of naïve CD4+ T cells induces Foxp3+ Tregs." (PMID 36358638, 2022). "We subsequently evaluated the landscape of FOXP3+ Tregs and CD68+ tumor-associated macrophages (TAMs) in HR/MMR-intact versus HR-d tumors." (PMID 35547873, 2022). "Dual immunofluorescence stainings of CD3 and FOXP3 on the tumor sections were analyzed for the number of Tregs (CD3+/FOXP3+) per tumor section using our developed software." (PMID 36176603, 2022).
tumor (continued). "Pharmacodynamic biomarkers were tested for CD38, PD-L1, tumor-infiltrating immune cells, and FOXP3+ regulatory T cells (Tregs) in the tumor microenvironment (TME)." (PMID 35987165, 2022). "USP7 inhibition stabilizes Foxp3, reduces Treg immunosuppression, and enables immune-mediated tumor suppression." (PMID 36428632, 2022). "If the number of <10 positives in the observation area is considered negative, 98 of the 106 cases included in this study (92%) were positive and showed a high frequency of FoxP3‐positive cells infiltrating the tumor tissue." (PMID 34319010, 2022). "In line with results from Asm-KO mice, we detected elevated percentages of tumor-infiltrating Foxp3+ Tregs as well as reduced frequencies of CD4+ and CD8+ T cells in dLNs from Asm/CD4cre mice compared to control littermates." (PMID 36426850, 2022). "This quantum dot-derivative labeled tumor-derived CD4+Foxp3+ Treg at higher extent than any other tumor-infiltrating T cell population in a mouse model of intracranial tumors." (PMID 35693776, 2022). "pCR/MPR patients displayed significantly higher density of CD3+, CD3+CD4+, CD20+, CD56 bright cell subsets and more tertiary lymphoid structures and significantly lower density of PD-L1+CD68+ and CD3+CD4+Foxp3+cells in the tumor or stroma." (PMID 36275670, 2022). "IL-9 is increasingly produced by tumor-infiltrating T cells (TILs), as well as tumor cells themselves and a subset of Foxp3 expressing regulatory T cells (Tregs)." (PMID 35681689, 2022). "In general, the percentages of FOXP3 Treg cells increased significantly in tumor tissues, which indicated a general suppression of T cell activities in SBA." (PMID 36104333, 2022). "This is supported by the fact that Nr4a factors sustain Treg cell lineage, at least in part, by positively regulating Foxp3 in both lymphoid Treg and tumor Treg cells." (PMID 35514961, 2022). "Double-labeling immunofluorescence confirmed that Foxp3+ Tregs expressed CCR4 in the tumor microenvironment." (PMID 35131860, 2022). "FOXP3+ Treg cells in the tumour microenvironment are regulated at multiple levels, which include Treg cell instability, Treg cell plasticity, and tissue Treg cell specificity." (PMID 36569832, 2022). "CD8+ T cells, FoxP3+ T cells, and MDSCs are assumed to get recruited everywhere, but with a higher probability at the IF of the tumor." (PMID 35867773, 2022). "Immuno-suppressive FOXP3+ regulatory T cells (Tregs) are present in tumour tissues, and they influence cancer growth and progression." (PMID 36613640, 2022). "Cox proportional hazard models were constructed to determine the association of abundance and spatial clustering of tumor-infiltrating lymphocytes (CD3+), cytotoxic T-cells (CD8+CD3+), and regulatory T-cells (CD3+FoxP3+) with overall survival." (PMID 35235563, 2022). "Single-cell classification was applied in tandem with a new method for DCIS ductal segmentation in dual-stained CA9 and FOXP3, whole-tumor section digital pathology images." (PMID 36109587, 2022). "Tumor-infiltrating FoxP3+ Tregs play a direct role in promoting immune evasion by upregulating markers associated with activation and enhanced suppressive activity, including cytotoxic T-lymphocyte-associated protein 4 (CTLA-4), PD-1, and CD255,6." (PMID 35058524, 2022). "LILRB4+ Tregs represent a small fraction of Foxp3+ cells in healthy peripheral blood but were found to be expanded in the circulation of allergic patients and in tumor infiltrating immune cells in various tumor models." (PMID 36591244, 2022). "Studies have found that solanine can enhance the anti-tumor immune response by down-regulating CD4+CD25+Tregs in tumor tissue and down-regulating the expression of Foxp3 and TGF-β." (PMID 36278230, 2022). "For the first time, we report that a high frequency of circulating CD4+FoxP3+Helios+ Tregs was associated with poorer DFS, while a high frequency of tumor-infiltrating CD4+FoxP3−Helios− T cells was associated with poorer DFS." (PMID 35655158, 2022).
tumor (continued). "Using the Gene Expression Omnibus dataset 89749 and TCIA, we identified CD8+/forkhead box P3 (FoxP3)+ tumour-infiltrating lymphocytes (TILs), T-cell immunoglobulin and mucin domain 3 (TIM-3) and human leukocyte antigen-A (HLA-A) in highly immunogenic ICCs." (PMID 35597869, 2022). "Our findings show that nuclear localization of FOXP3 is more common in tumor patients’ lymphocytes than in normal lymphocytes, implying that it plays a dynamic role as a transcription factor." (PMID 35222362, 2022). "As a transcription factor associated with development of regulatory T cells and, due to our results showing elevated CFH in these tumor samples, we expected FOXP3 staining to be more intense within the immune infiltrate surrounding tumor tissue (arrows)." (PMID 35223500, 2022). "In human CD4+ T cells, miR-138 represses PD-1, CTLA-4, and FoxP3 expression, and in vivo administration of miR-138 mimics to tumor-bearing mice led to enhanced T-cell–mediated tumor immunity and survival." (PMID 36248881, 2022). "CD4+CD25+Foxp3+ Tregs are the immunosuppressive cells related to the tumor progression, invasiveness, as well as metastasis." (PMID 35493518, 2022). "For instance, higher density of infiltrating tumor T regulatory FOXP3 cells was shown to negatively affect prognosis in breast cancer." (PMID 35963999, 2022). "The presence of tumor-infiltrating mast cells and FOXP3+ Tregs was correlated with the downregulation of HLA-I molecules on tumor cells, resulting in the lack of CD8+ T-cell infiltration in these tumor regions." (PMID 35444656, 2022). "After 30 days of observation, we noticed that circRUNX1 overexpression groups showed significantly faster tumor growth than the other two groups, while inhibition of FOXP3 in circRUNX1-overexpressing cells restricted tumor growth." (PMID 36522683, 2022). "Analysis of tumour‐infiltrating lymphocytes revealed a significant fraction of FOXP3+ and PD‐1+FOXP3+Tregs in antagomir NC group compared with antagomir group (p < .001)." (PMID 35969010, 2022). "We found that after TDO2 inhibition, in the proximal region from the tumor nests (<20 μm), the proportions of Tregs (Foxp3+CD4+) in CD4+ T cells and exhausted CD8+ T cells (TIM-3+CD8+) in CD8+ T cells were significantly reduced (P < 0.05)." (PMID 35972800, 2022). "It has been suggested that CD103+CD8+ T cells represent a tolerant T cell subset and express Foxp3 at RNA level in a similar B16 tumor model." (PMID 36229613, 2022). "In our signature, the expression of STAT1 and FOXP3 is the main indicator of anti‐tumour response through sustaining T‐cell population which is tumour suppressive." (PMID 35043584, 2022). "Tregs express the transcription factor Foxp3, maintain the immune homeostasis, and prevent the initiation of anti-tumor immune effects in various ways as their mechanisms to modulate tumor development." (PMID 35371055, 2022). "FoxP3 was positive in only 1–5% of tumor-infiltrating lymphocytes in 77% of cases; in the remaining cases, FoxP3 was positive in 10–50% of tumor-infiltrating lymphocytes." (PMID 35205136, 2022). "Investigation of the Treg cells from both the TDLN and tumor tissues revealed downregulation of Foxp3 and CTLA-4 in the Foxp3CreNr4a-DcKO mice when compared with the wild-type mice." (PMID 35514961, 2022). "FACS and IHC analyses showed that recruitment of CD3 + /CD8 + cytotoxic T cells, which suppress cancer cells, increased and that tumor-friendly CD3 + /CD4 + /FoxP3 + T cells decreased upon co-treatment with PLAG + aPD-L1." (PMID 35787261, 2022). "The majority of tumors had detectable FOXP3+ Tregs in pre-treatment tumor (20 of 25 evaluable, 80%)." (PMID 34991708, 2022). "Tumour-infiltrating FOXP3+RORγt+ Treg cells suppress FoxO3 in DCs, leaving IL-6 expression uncontrolled." (PMID 36569832, 2022). "Analogous to this, tumor regions with low levels of CD8+ cells were characterized by low densities of FoxP3+ and CD163+ cells." (PMID 36551693, 2022).
tumor (continued). "CD4+FoxP3+ Tregs expressing CD39 repressed anti-tumor immunity by NK cells and pharmacologic inhibition of CD39 significantly limited melanoma tumor growth." (PMID 35360246, 2022). "IF results showed reduced accumulation of FOXP3+ and PD‐1+ FOXP3+Tregs in the tumours of the miR192‐5p antagomir group." (PMID 35969010, 2022). "Combination therapy significantly reduced tumor infiltration of immunosuppressive CD4+/CD25+/FOXP3+ Tregs." (PMID 35392977, 2022). "The tumor size and weight, gene expression (IL10, INF-γ, TGFβ, and FOXP3), and pathological properties of the tumor and normal tissues were assessed." (PMID 36544523, 2022). "Both tumor and peritumor tissue had higher Foxp3+ICOS+/Foxp3+ cell ratio when compared with normal tissue." (PMID 35311157, 2022). "A higher ratio of FOXP3+/CD3+ was just observed in the tumor tissues of patients with stage III compared to stage I (P = 0.031); however, it did not resist Bonferroni correction." (PMID 36038861, 2022). "In summary, the FOXP3 gene will prove to be a useful target that can bring about new ideas for tumor-targeted therapy." (PMID 36235242, 2022). "Tumour-infiltrating FOXP3+ Treg cells exhibit higher glycolysis, which hastens glucose consumption and reduces glucose availability within TME." (PMID 36569832, 2022). "Just under 10% of tumor-infiltrating CD4+ T cells expressed FOXP3 by flow cytometry across measured samples." (PMID 35584630, 2022). "We further analyzed the production of IFN-γ, IL-4, IL17a, and Foxp3 in lymphocytes separated from the tumor tissues, which reflects the population of Th1, Th2, Th17, and Treg cells, respectively." (PMID 36209170, 2022). "In this study, we report that a high frequency of circulating CD4+FoxP3+ Tregs was associated with poorer disease-free survival (DFS), while their higher frequencies in tumor-infiltrating CD4+ Tregs was associated with better DFS." (PMID 35655158, 2022). "In some tumor entities FoxP3 has also been described as being expressed by the tumor cells themselves, but the existing literature is not conclusive here." (PMID 36098901, 2022). "On the other hand, Tregs (Foxp3+ CD25+ CD4+ T cells) have been shown to be recruited by tumor cells in TME to fight antitumor immunity." (PMID 35444656, 2022). "We examined the feasible connection between the clearance of tumor cells and the alteration of FOXP3+ Tregs in the Th cell repertoire." (PMID 35444547, 2022). "Here, in cDC1-deficient hosts, CD40 agonist primed tumor-specific T cells that coexpressed Klrg1 and Lag3, or a Treg marker Foxp3, and these T cells appeared dispensable for tumor control." (PMID 35393950, 2022). "With a combination of in vivo and in vitro approaches, we show that B7x expands tumor-infiltrating Treg populations by inducing the expression of the Treg-specific transcription factor Foxp3 in conventional CD4+ T cells and converting them into Tregs." (PMID 35523809, 2022). "These STAT1-positive tumors also exhibited a high degree of immune cell infiltration, especially CD4-, CD8, and FOXP3-positive T cells, suggesting that an active engagement of the immune system with the tumor takes place and that these tumors are immune “hot”." (PMID 35267462, 2022). "FOXP3, as a major transcription factor involved in the development and function of Tregs, can induce tumor immune escape in the tumor microenvironment (TME)." (PMID 36235242, 2022). "In melanoma patients, the ratio of cytotoxic CD8+ T cells versus CD4+Foxp3+ regulatory T cells (Tregs) in the tumor microenvironment is predictive for the disease outcome." (PMID 36426850, 2022). "Previously, studies focusing on Treg-like cells suggested that FOXP3+ Tregs have a tumor suppressive role in the pathogenesis of MF/SS, but the results have been discordant and conflicting." (PMID 35406628, 2022).
tumor (continued). "We compared proportions of CD3+, CD4+, and CD8+ T cells, CD57+ natural killer (NK) cells, CD4+ FOXP3+ regulatory T cells (Tregs), and CD68+ CD163+ M2 tumor-associated macrophages (TAMs) between paired ACC and SCCC samples, respectively." (PMID 36032124, 2022). "Regulatory T (Treg) cells are featured by an increasing amount of FOXP3 content and are recruited in the tumor microenvironment to eradicate obstacles to tumor growth." (PMID 36301031, 2022). "Tumor immune estimation resource database was used to analyze the mRNA expression of FOXP3 in pan cancer, and to analyze the correlation between FOXP3 expression and tumor microenvironment cell infiltration." (PMID 36550816, 2022). "We also evaluated the tumor microenvironment topography of FOXP3+ Tregs and CD68+ TAMs, since their immunosuppressive properties counterpoise the anti-tumor effect of cytotoxic CD8+ T-lymphocytes." (PMID 35547873, 2022). "Surgical resection of tumors after CAR T cell infusion revealed that, although the cells were able to traffic to the tumor site, there was also an influx of Tregs into the tumor, accompanied by the increase of immunosuppressive markers such as FOXP3 and PD-L1." (PMID 36284838, 2022). "Our research identifies a FOXP3+ Treg population in tumor-infiltrating CD4+ lymphocytes that are largely CCR4+." (PMID 35222362, 2022). "Accumulation of Foxp3+ Tregs within tumor tissue and/or draining lymph nodes was confirmed as the negative prognostic factor in many solid tumors, including lung and colon cancer." (PMID 36428632, 2022). "For example, FOXP3 overexpression in Treg cells can inhibit the tumour immune response and promote the proliferation of tumour cells." (PMID 35281860, 2022). "We detected more FOXP3+ Tregs in tumor tissues than in adjacent normal tissues, Peripheral blood mononuclear cells (PBMCs) and lymph nodes." (PMID 35354899, 2022). "Further results showed that the number of regulatory T cells (Treg) (CD4+CD3+Foxp3+) decreased, the immunosuppressive tumor microenvironment was relieved, and immune T cells induced antitumor immunity was activated." (PMID 35651605, 2022). "Foxp3- CD4+ helper T cells have been shown to promote the priming of tumor-specific CD8+ T cells and help elicit durable T cell responses by interacting with dendritic cells in an MHCII-dependent manner." (PMID 36237314, 2022). "In our cohort of 82 patients, the presence of Foxp3+ T cells in the tumor microenvironment had the same predictive ability for OS." (PMID 35197968, 2022). "In untreated CT-26 tumor-bearing animals, there was a notable increase in the density of tSNE regions that mapped to the expression of FoxP3, CD25, TGF-β, and NRP-1." (PMID 36090972, 2022). "The expression of FOXP3 and IL-10 mRNA was obviously decreased in the tumor-bearing mice of the treatment group, while the secretion of IL-12 was increased and the contents of IL-10 and TGF-β were decreased." (PMID 36235242, 2022). "Except for the FOXP3‐rich cluster, all immune clusters demonstrated higher PD‐1 expression levels in intra‐tumor CD8 T‐lymphocytes compared with their stromal counterparts." (PMID 36169332, 2022). "In contrast to other solid tumors, high levels of tumor-infiltrating FoxP3+ Tregs were related to increased survival in CRC patients." (PMID 35455287, 2022). "We initially compared the densities of CD8+ T cells, FOXP3+ Treg cells, PD-1+ and PD-L1+ cells between tumor tissue and paired adjacent normal tissues." (PMID 35222387, 2022). "LAYN+ Tregs showed highly expressed LAYN, TNFRSF9, and ICOS, but the proportion of this cell population in tumor‐infiltrating cells was very small, which was different from FOXP3+ Tregs." (PMID 35474948, 2022). "CD163+M2 macrophages and Foxp3+Tregs were mainly distributed in the interstitium of tumor tissues and lymphocyte aggregates in PTC and mainly scattered around cancer cells in ATC." (PMID 35222534, 2022).